PARK7 (Parkinsonism associated deglycase)
Diseases named in the same sentence as PARK7 in open-access papers (continued):
Sharing a sentence is not in itself a finding about the gene and the disease.
tumor (94 papers, 2004 to 2025). "The inhibition of DJ-1 (also known as Parkinsonism-associated deglycase, PARK7) enhances tumor cells' sensitivity to ferroptosis inducer via disrupting the formation of the S-adenosyl homocysteine hydrolase (SAHase) and impairing its activity." (PMID 33425217, 2020). "PARK7 activates various intracellular signaling pathways that have been implicated in the induction of tumor progression, which subsequently enhances tumor initiation, continued proliferation, metastasis, recurrence, and resistance to chemotherapy." (PMID 32357493, 2020). "Studies have shown that increased levels of PARK7 in 85% of LSC patients are linked to poor survival and tumor recurrence in the LSC patients." (PMID 40231252, 2025). "We further explored the correlation observed between SNCA and PARK7 expression in SKCM primary tumor patients using the transcriptomic TCGA data (N = 102)." (PMID 38189631, 2024). "The heat map showed that the expression of DEGs in which FKBP3 and PARK7 were highly expressed in the tumour." (PMID 37987202, 2024). "In a clinical context, analysis of data from the TCGA database revealed that PARK7 was significantly more highly expressed in tumor tissues compared to adjacent non-tumor tissues." (PMID 39276379, 2024). "Our results indicated that FKBP3 and PARK7 increased the stemness of DLBCL cells accordingly promoting tumour growth, and they were positively correlated." (PMID 37987202, 2024). "Intriguingly, PARK7 overexpression substantially increased cell growth in EFCAB7 knockdown tumor cells." (PMID 39276379, 2024). "The effect of PARK7 in balancing tumor cell survival and normal cell physiology merits further research." (PMID 38304232, 2023). "Consistent with the TCGA data analysis results, GEO data (GSE53625) analysis also showed that DJ-1/PARK7 was highly expressed in ESCC tumor tissues." (PMID 36008860, 2022). "Elevated PARK7 expression has been found in a variety of tumours and correlates with survival of TCs." (PMID 34771736, 2021). "This review summarizes the current understanding of the correlation between the expression of PARK7 and tumor progression." (PMID 32357493, 2020). "Although the overexpression of NRG1 and ERBB3 drastically increases the serum levels of PARK7 and in vivo tumor formation, it markedly reduces the intratumoral expression of PARK7." (PMID 32357493, 2020). "Meanwhile, frequently deleted genomic regions included tumour suppressor genes such as PARK7 (1p36.23), CDKN2A (9p21.3), and PTEN (10q23.3)." (PMID 32762688, 2020). "Genes associated with the SEs in tumor cells were mostly related to transcription (e.g., POLR2E, PARK7, MYC)." (PMID 33168807, 2020). "The serum levels of PARK7 are significantly increased in NSCLC, and this increase in the levels of PARK7 has been identified as a high-risk factor that determines the tumor stage and metastasis of NSCLC." (PMID 32357493, 2020). "Recent studies have identified positive modulators of PARK7 expression that enhance tumor progression." (PMID 32357493, 2020). "PARK7 induces tumor progression by regulating the expression of oncoproteins and tumor suppressor proteins." (PMID 32357493, 2020). "At the level of differentiation, the enhanced expression of PARK7 in MD/PD/WD metastatic OSCC compared to keratinized WD OSCC supports tumor progression and is correlated with a poor clinical outcome." (PMID 32922662, 2020). "Parkinson disease protein 7 (PARK7/ DJ-1) expression is elevated in various tumors and related to the survival of tumor cells under adverse stimuli, including oxidative stress." (PMID 31640265, 2019). "Furthermore, we found that PARK7 overexpression enhanced cell migration in EFCAB7 knockdown tumor cells." (PMID 39276379, 2024). "Finally, when we overexpressed PARK7 in EFCAB7 knockdown tumor cells, it rescued proliferation and metastasis, indicating a functional relationship between these two genes." (PMID 39276379, 2024).
tumor (continued). "In addition, we also identified significant up-regulation of Hyp on glycolysis enzymes pyruvate kinase (PKM), enolase (ENO1), and autophagy protein Parkin (PARK7) in tumor tissue." (PMID 36026437, 2022). "PARK7 is also a “redox sensor” that protects tumor cells from OS." (PMID 36500393, 2022). "Since PARK7 expression was higher in TC with an increased mitotic activity, it might be related to tumour cell proliferation, and thus be used to monitor this process." (PMID 34771736, 2021). "PARK7 is upregulated in 83.3% of patients with cholangiocarcinoma and in 85% of patients with laryngeal squamous cell cancer, which is significantly correlated with the poor survival and tumor recurrence of patients with laryngeal squamous cell cancer." (PMID 32357493, 2020). "Previous studies have demonstration that PARK7 knockout (KO) mice showed a drastic reduction in both the number of tumors and tumor size by increasing the expression of phosphatase and tensin homolog deleted on chromosome 10 (PTEN) and decreasing the activation of AKT." (PMID 32357493, 2020). "Several negative regulators inhibit the expression of PARK7 for suppressing tumor progression." (PMID 32357493, 2020). "Additionally, PARK7 expression was found to be increased in tumor tissues after RFA treatment." (PMID 39276379, 2024). "Meanwhile, PARK7 (DJ–1), although taking part in the UPS, antagonizes the tumor-suppressor gene PTEN in dividing cells." (PMID 35741059, 2022). "PARK6, PARK7, PARK8, and PARK15 mRNA expression were found to have significant difference in the comparison of different tumor stages." (PMID 26245297, 2015). "Five genes PARK5 (91.23 %), PARK6 (83.33 %), PARK7 (70.18 %), PARK9 (87.72 %), and GBA (86.84 %) were supposed to be overexpressed in the lung tumor tissues compared with tumor-adjacent tissues." (PMID 26245297, 2015). "Then, the five genes PARK5 (91.23 %), PARK6 (83.33 %), PARK7 (70.18 %), PARK9 (87.72 %), and GBA (86.84 %) were supposed to be overexpressed in the lung tumor tissue compared with the tumor-adjacent tissue." (PMID 26245297, 2015). "Excessive ROS production by T15 treatment activates different counter mechanisms trying to partially protect the tumor cells against oxidative stress, such as the higher expression of NOX1 on MCF7 cells; PARK7, PRDX1 and PRDX3 on MDA-MB231 cells; and UCP1 elevation in PANC1 cells." (PMID 41011284, 2025). "Notably, PARK7+Mac−C2 and VIM+Mac−C1 exhibited a preference for expressing genes that were upregulated in M1 macrophages, suggesting their enhanced M1-like anti-tumor functions." (PMID 38095634, 2023). "Treatment with dimethyl fumarate suppresses the tumor formation and proliferation of CRC cells by inducing oxidative stress and reducing the intracellular levels of glutathione, by reducing the expression of PARK7, which depletes GABPA." (PMID 32357493, 2020). "One hundred and fourteen matched human NSCLC tumor/normal pairs were examined by real-time q-PCR analysis for expression of PARK1/4 (SCNA), PARK2 (Parkin), PARK5 (UCHL1), PARK6 (PINK1), PARK7 (DJ-1), PARK8 (LRRK2), PARK9 (ATP13A2), PARK15 (FBXO7), and GBA mRNA." (PMID 26245297, 2015). "The high expression of PARK6, PARK7, and PARK15 might lead to the occurrence of a primary NSCLC tumor, and the tumor with a decreasing expression of these three genes tends to be stages II and III." (PMID 26245297, 2015). "The high expression of PARK6, PARK7, and PARK15 might lead to the occurrence of a primary tumor, but the tumor with a decreasing expression of PARK6 and PARK15 tends to be the stages II and III tumor." (PMID 26245297, 2015). "As such, rather than functioning as a tumor suppressor, PARK7 may be considered an oncogene." (PMID 35741059, 2022).
neurodegenerative disease (70 papers, 2006 to 2026). A disorder of the central nervous system characterized by gradual and progressive loss of neural tissue and neurologic function. "One of the well-studied neurodegenerative diseases, such as Parkinson’s disorder (PD), is caused by genetic mutations in the PARK7 gene, which encodes for DJ-1." (PMID 40608842, 2025). "Moreover, it can be suggested that intestine-derived systemic inflammation impairs the function of PARK7/DJ-1 in the CNS, thereby increasing the risk of the development of neurodegenerative diseases." (PMID 35743072, 2022). "PARK7 (DJ-1), initially recognized for its role in neurodegenerative diseases, has been identified in the colonic mucosa of IBD children, suggesting its involvement in intestinal inflammation." (PMID 39144148, 2024). "The connection between PARK7/DJ-1 and neurodegenerative diseases was first suggested nearly two decades ago when it was identified as a causative factor in rare inherited forms of PD." (PMID 35743072, 2022). "Experimental data suggest that PARK7/DJ-1 plays a protective role in neurodegenerative diseases via its antioxidant properties." (PMID 35743072, 2022). "In the past decade, the role of Parkinson’s disease 7 (PARK7/DJ-1) has been demonstrated in neurodegenerative diseases." (PMID 35743072, 2022). "Parkinson's disease 7 (PARK7) is a multifunctional molecule, which is primarily investigated in connection with neurodegenerative diseases; however, its possible role has been suggested in other diseases, as well." (PMID 32963695, 2020). "PARK7 is an ubiquitously expressed antioxidant protein, in which significance is clearly demonstrated in the pathomechanism of different neurodegenerative diseases." (PMID 32963695, 2020). "About half of the neurodegenerative disease-associated genes, namely APP, PSEN1, and PSEN2 for AD; C9orf72 and MAPT for FTD and SNCA; and PRKN and PARK7 for PD, have larger number of DPI robust TSSs than annotated CAT CAGE clusters." (PMID 30610612, 2019). "Finally, since the association of the intestinal microbiome and also that of PARK7/DJ-1 with neurodegenerative diseases is well known, they investigated the molecular biological changes in the midbrain of PARK7/DJ-1−/− mice by RNA-sequencing." (PMID 35743072, 2022). "Glyoxalase activity of PARK7/DJ-1 in neuroprotection may also be of great importance since AGEs have been suggested to contribute to the development of neurodegenerative diseases." (PMID 35743072, 2022). "Since then, the role of PARK7/DJ-1 in neurodegenerative diseases has been intensively studied, and it has become clear that PARK7/DJ-1 may play a role not only in PD but in almost all neurological diseases associated with oxidative stress, inflammation, and tissue damage." (PMID 35743072, 2022). "DJ-1, also called Parkinson’s protein 7 (PARK7), is ubiquitously expressed and plays multiple actions in different physiological and, especially, pathophysiological processes, as evidenced by its identification in neurodegenerative diseases and its high expression in different types of cancer." (PMID 35563738, 2022).
infection (15 papers, 2011 to 2025). The state of being infected such as from the introduction of a foreign agent such as serum, vaccine, antigenic substance or organism. "The diagnostic sensitivity and specificity of PARK7 and CDH16 were higher than those of neutrophil gelatinase-associated lipocalin (NGAL), which was used to diagnose AKI, particularly infection-mediated AKI." (PMID 32194432, 2020).
adenocarcinoma (3 papers, 2011 to 2015). A common cancer characterized by the presence of malignant glandular cells. "Similarly, elevated levels of an additional Parkinson's disease associated protein PARK7 (DJ1), in pancreatic ductal juice of adenocarcinomas corroborate an earlier report." (PMID 21448452, 2011).
gastrointestinal disease (3 papers, 2021 to 2025). A disease that occurs in the gastrointestinal system, excluding the hepatobiliary system. "Recently the role of Parkinson’s disease 7 (PARK7) was studied in gastrointestinal diseases, however, the complex role of PARK7 in the intestinal inflammation is still not completely clear." (PMID 34272410, 2021). "However, there are a few studies investigating the role of PARK7 in gastrointestinal diseases." (PMID 34272410, 2021).
renal diseases (3 papers, 2020 to 2025). "Compared to control animals, altered PARK7 levels in kidney tissues have also demonstrated in experimental animal of kidney diseases." (PMID 34093596, 2021). "Collectively, these studies indicate that renal tubular cell PARK7 has an anti-fibrotic, protective function in kidney diseases." (PMID 34093596, 2021). "Recent studies have suggested a role of PARK7 in the development of kidney diseases." (PMID 34093596, 2021).
brain disease (2 papers, 2016 to 2022). "Based on our current knowledge, it is assumed that PARK7/DJ-1 represents a molecular link between intestinal and brain diseases." (PMID 35743072, 2022). "Based on the increasing number of data demonstrating the protective role of PARK7/DJ-1 in both the gut and brain diseases, our review aims to point out how PARK7/DJ-1 may connect the pathologies of the two organs." (PMID 35743072, 2022). "All these findings suggest that PARK7/DJ-1 may be a link and also a potential therapeutic target in gut and brain diseases." (PMID 35743072, 2022).
digestive system disorder (2 papers, 2022 to 2024). A disease or disorder that involves the digestive system. "Besides the beneficial functions of PARK7/DJ-1 in the CNS, it has recently come into the focus of interest also in connection with gastrointestinal disorders." (PMID 35743072, 2022).
infectious disease (2 papers, 2021 to 2025). A disorder directly resulting from the presence and activity of a microbial, viral, or parasitic agent in humans. "Collectively, our results demonstrate a role for PARK7 in regulation of inflammation and cellular homeostasis and suggest that PARK7 deficiency may aggravate infectious disease and cause immunopathology." (PMID 41675199, 2025).
immune disorders (1 paper, 2022). "Parkinsonism-associated deglycase-PARK7/DJ-1 (PARK7) is a multifunctional protein having significant roles in inflammatory and immune disorders and cell protection against oxidative stress." (PMID 35207708, 2022). "Parkinsonism-associated deglycase-PARK7/DJ-1 (PARK7) is a multifunctional protein that plays a crucial role in inflammatory diseases, immune disorders, and cell protection against oxidative stress." (PMID 35207708, 2022).
intestinal diseases (1 paper, 2022). "However, in the present section, we focus on the recently emerged role of PARK7/DJ-1 in the pathomechanism of intestinal diseases." (PMID 35743072, 2022).
neuromuscular disease (1 paper, 2024). "However, PARK7 variants may also cause various non-motor symptoms, psychiatric symptoms, and neuromuscular diseases with different variants and disease durations." (PMID 39170205, 2024).
PARK7 also shares sentences with these, for which no sentence is quoted: amyotrophic lateral sclerosis (17 papers); synucleinopathies (12); endometrial cancer (9); Hypertension (9); neurological diseases (8); cardiovascular disease (7); diabetic nephropathy (7); esophageal squamous cell carcinoma (7); cardiac hypertrophy (6); gastric cancer (6); heart failure (6); ischemic heart disease (6); myocardial infarction (6); myocardial ischemia (6); osteosarcoma (6); atherosclerosis (5); Hyperglycemia (5); bladder cancer (4); Cognitive impairment (4); multiple sclerosis (4); multiple system atrophy (4); viral infection (4); Anxiety (3); brain inflammation (3); brain injury (3); colorectal tumor (3); emphysema (3); invasive ductal carcinoma (3); lung disease (3); metabolic disorders (3).
A further 167 diseases each share a sentence with PARK7 in 3 papers or fewer.